USP25 (ubiquitin specific peptidase 25)
Description:
Deubiquitinating enzyme that hydrolyzes ubiquitin moieties conjugated to substrates and thus, functions in various biological processes including inflammation and immune response. Modulates the Wnt/beta-catenin pathway by deubiquitinating and stabilizing tankyrases TNKS1 and TNKS2. Regulates KEAP1-NRF2 axis in the defense against oxidative assaults by deubiquitinating KEAP1 and protecting it from degradation leading to degradation of the NRF2 transcription factor that is responsible for mounting an anti-oxidation gene expression program. Positively regulates RNA virus-induced innate signaling by interacting with and deubiquitinating ERLIN1 and ERLIN2. In turn, restricts virus production by regulating cholesterol biosynthetic flux. Acts as a negative regulator of interleukin-17-mediated signaling and inflammation through the removal of 'Lys-63'-linked ubiquitination of TRAF5 and TRAF6. Prevents the ubiquitination and degradation of TRAF3 to reduce the phosphorylation levels of JNK and P38, the secretion of IL-1B and to induce endotoxin tolerance. The muscle-specific isoform (USP25m) may have a role in the regulation of muscular differentiation and function.
Synonyms: USP21; EIG19
Tractability: Small molecule: a high-quality ligand is known. PROTAC: UniProt records ubiquitination sites on it; ubiquitination databases record sites on it; its protein half-life has been measured; a small molecule that binds it is known.
Target class: Enzyme; Hydrolase
Gene: Protein-coding gene on chromosome 21 (15,729,925 to 15,880,064, forward strand). Ensembl gene ENSG00000155313.
Subcellular location: Cytoplasm; Cytoplasm (Isoform USP25m); Nucleus
Subcellular location (Human Protein Atlas): Cytosol
Pathways (Reactome):
Metabolism of proteins: Ub-specific processing proteases
Gene Ontology:
Molecular function: ATPase binding; cysteine-type deubiquitinase activity; deubiquitinase activity; protein binding; SUMO binding; ubiquitin protein ligase binding; peptidase activity; ubiquitin binding; ubiquitin-like protein peptidase activity
Biological process: negative regulation of ERAD pathway; negative regulation of interleukin-17-mediated signaling pathway; negative regulation of response to oxidative stress; protein deubiquitination; protein K48-linked deubiquitination; protein K63-linked deubiquitination; protein modification process; proteolysis; immune response; interleukin-17-mediated signaling pathway; mRNA metabolic process; protein-containing complex assembly; response to oxidative stress; stress-activated protein kinase signaling cascade
Cellular component: cytoplasm; cytosol; endoplasmic reticulum; nucleus
Genetic constraint (gnomAD): Loss-of-function variants: 64 observed, 124.14 expected, observed/expected ratio (o/e) 0.52, 90% interval 0.42 to 0.63. The upper end of that interval is the gene's LOEUF score, 0.63, which puts it in group 2 of 6, group 1 being the genes least tolerant of losing a copy. Missense variants: 1,053 observed, 1,178.8 expected, observed/expected ratio (o/e) 0.89, 90% interval 0.85 to 0.94. Synonymous variants: 397 observed, 418.12 expected, observed/expected ratio (o/e) 0.95, 90% interval 0.87 to 1.03.
Gene-disease validity (ClinGen):
ClinGen rates the evidence that USP25 causes each of these diseases.
epilepsy (autosomal dominant): Disputed. A brain disorder characterized by episodes of abnormally increased neuronal discharge resulting in transient episodes of sensory or motor neurological dysfunction, or psychic dysfunction.
Homologues: Orthologues: chimpanzee USP25 (99% identical), macaque USP25 (99% identical), dog USP25 (97% identical), pig USP25 (97% identical), rabbit USP25 (97% identical), guinea pig USP25 (96% identical), rat Usp25 (94% identical), mouse Usp25 (93% identical), tropical clawed frog usp25 (81% identical), zebrafish usp25 (73% identical). Paralogues in human: USP28 (50% identical), USP9X (14% identical), USP24 (14% identical), USP9Y (13% identical), USP43 (12% identical), USP31 (12% identical), USP48 (11% identical), USP36 (11% identical), USP19 (11% identical), USP38 (11% identical), USP32 (10% identical), USP15 (10% identical), and 59 more.
Diseases named in the same sentence as USP25 in open-access papers:
USP25 is named in the same sentence as 79 diseases in open-access papers, as found by Europe PMC text mining. Sharing a sentence is not in itself a finding about the gene and the disease. The quoted sentences say what the papers report.
viral infection (12 papers, 2013 to 2024). "USP25 deficient mice have been shown to be more susceptible to virus infection and LPS-induced septic shock.IL-17-mediated inflammation is also attenuated by USP25 through TRAF5 and TRAF6 deubiquitination." (PMID 32650621, 2020). "report that Usp25, a deubiquitylase, is able to restrict virus infection by stabilizing the Erlin1/2 complex, which in turn regulates intracellular cholesterol levels." (PMID 37683630, 2023). "In order to investigate the function of Usp25 during viral infection, we first generated Usp25−/− cells using CRISPR/Cas9 technology." (PMID 37683630, 2023). "Since miR-200c was upregulated following virus infection, we confirmed the role of miR-200c in the regulation of CNTN1 and USP25 in miR-200c-deficient cells." (PMID 35171955, 2022). "Lipopolysaccharides and viral infections activate USP25 transcription through signals triggered by type I interferon (IFN)." (PMID 35096833, 2021). "We first screened the reported deubiquitinases for TRAF3 and found that HSCARG interacted with OTUB1 more potently than OTUB2, UCHL1, OTUD7B, and USP25, and this interaction was enhanced by viral infection." (PMID 24763515, 2014). "Previous studies have shown that the type I interferon-IRF7 axis can mediate the transcription of the USP25 gene after viral infection or lipopolysaccharide treatment and that miRNA-200c can reduce both the messenger RNA and protein levels of USP25 in non-small cell lung cancer." (PMID 39395794, 2024). "Intriguingly, USP25 induced by viral infection prevents TRAF3 and TRAF6 from degradation." (PMID 37888853, 2023). "Confocal microscopy showed that CNTN1 and USP25 colocalized and dispersed throughout the cytoplasm without virus infection, which had a partial association with MAVS." (PMID 35171955, 2022). "In addition, USP25 is upregulated after viral infection and participates in the body’s antiviral response by mediating the stabilization of tumor necrosis factor (TNF) receptor associated factor 3 (TRAF3) and TRAF6." (PMID 35096833, 2021). "In this study, we have identified a key role of Usp25 in limiting cholesterol biosynthetic flux to trigger TLR3-dependent immune activation and restrict virus infection." (PMID 37683630, 2023). "For example, USP25 was reported to be able to enhance the stability of TRAF3 and TRAF6, thus promoting IFNs induction by viral infection." (PMID 29734366, 2018).
breast carcinoma (7 papers, 2014 to 2025). "Recently, USP25 has been associated to several types of cancer such as breast cancer, lung cancer, and non-small-cell lung cancer and the P535L mutant would render USP25 more active than the wild type by destabilizing the tetramer assembly." (PMID 30478318, 2018). "Similar results were obtained after knockdown of USP25 in various cancer cell lines, including breast cancer cell lines (MDA-MB-231 and T47D), non-small cell lung cancer (NSCLC) cell lines (A549 and H1299), and osteosarcoma cell lines (U2OS)." (PMID 41321637, 2025). "USP25 is over-expressed (>threefold) in breast cancer tissue compared to adjacent normal breast tissue." (PMID 34249948, 2021). "USP25 has been informed to be vastly expressed in human breast cancer tissues with a 3-fold change, and USP25 may be a human lung cancer tumor suppressor." (PMID 35450028, 2022). "As with USP10, additional studies in breast cancer are needed for USP25." (PMID 25606592, 2014). "Moreover, a genome-wide association study (GWAS) of breast cancer declared identification of 65 novel loci associated remarkably with a high risk of breast cancer at P < 5 × 10− 8 such as FES, MAP 3 K11, CLK2, GRK7, USP25, DFFA, PKP1, and ZKSCAN3." (PMID 35650591, 2022). "But few studies have been performed to determine the significance of USP25 in tumor metastasis; SMURF2 is known to suppress tumor angiogenesis and metastasis, However, others reported that SMURF2 promoted metastasis in breast cancer cells." (PMID 24997798, 2014). "An analysis of differential USP gene expression in breast cancer found greater than threefold overexpression of USP9X, USP10 and USP25 in human breast cancer tissue as compared with adjacent normal tissue." (PMID 25606592, 2014).
Alzheimer disease (6 papers, 2012 to 2023). A progressive, neurodegenerative disease characterized by loss of function and death of nerve cells in several areas of the brain leading to loss of cognitive function such as memory and language. "For example, USP25 deficiency attenuates microglia-mediated proinflammatory cytokine overproduction and synapse elimination in Alzheimer’s disease." (PMID 37814350, 2023). "Recent studies have shown that USP25 plays a key role in microglial homeostasis reprogramming in Alzheimer’s disease and DS." (PMID 34992628, 2021). "In short, USP25 plays a promoting role in the development of Alzheimer’s disease." (PMID 34249948, 2021). "In silico analyses of miRNA target prediction unveiled that miR-455-3p had a strong capacity to bind to USP25, and human miRNA-455-3p thus might serve as a peripheral biomarker of Alzheimer’s disease." (PMID 34249948, 2021). "As another deubiquitinase, USP25 can take part in many diseases, not only cancers but also Alzheimer’s disease and antiviral immunity, suggesting that inhibitors of both USP25 and USP28 may influence other biological or pathological processes mediated by the lack of USP25." (PMID 36879346, 2023). "Our observations that USP25 interacted with APP and affected APP turnover implicate USP25 in Alzheimer's Disease pathogenesis and may serve as a point of intervention for new therapeutic strategies." (PMID 22590560, 2012).
cardiac hypertrophy (5 papers, 2024 to 2025). "USP25 is elevated in hypertrophic myocardium, where it stabilizes SERCA2a by removing K48-linked ubiquitin chains, thereby inhibiting cardiac hypertrophy." (PMID 40158182, 2025). "Recently, our group found that USP25 in cardiomyocytes negatively regulates pathological myocardial hypertrophy in hypertensive mice." (PMID 39985261, 2025). "To avoid the off-target effect of OB in cardiac hypertrophy, we measured the effect of OB on the USP25 deubiquitinating SERCA2a." (PMID 39431010, 2024). "Interestingly, our group has recently reported that USP25 improves pathological myocardial hypertrophy by deubiquitinating SERCA2a and increasing SERCA2a stability in cardiomyocytes." (PMID 39985261, 2025). "Interestingly, in many cases, USP28 and USP25 play opposite roles in the same disease, such as cardiac hypertrophy, where USP25 is a protective protein 21 but USP28 promotes this disease development." (PMID 39431010, 2024).
lung carcinoma (5 papers, 2016 to 2024). "Here, USP25 was found to be frequently downregulated and was located in regions commonly deleted in human lung cancer." (PMID 34249948, 2021). "Moreover, lung cancer cells in which USP25 was knocked down had diminished migration and invasion abilities." (PMID 34249948, 2021). "In lung cancer, miR-200c inhibits cancer cell invasion through the ubiquitin specific peptidase 25 (USP25) protein, which is a peptidase primarily associated with protein ubiquitination and may intervene with TGFβ signaling and EMT." (PMID 27601996, 2016).
cognitive deficits (4 papers, 2022 to 2025). "USP25 is implicated in activating microglia, and its overexpression allows the de-ubiquitination of a series of molecular substrates that have been associated to synaptic abnormalities and associated cognitive deficits." (PMID 35585302, 2022). "Genetic deletion or pharmacological inhibition of USP25 enhances Aβ-induced synapse phagocytosis, restores microglial homeostasis, and reduces neuroinflammation and cognitive impairment in AD mice, highlighting USP25 as a promising therapeutic target for AD." (PMID 39562545, 2024). "Overexpression of USP25 resulted in microglial activation and induced synaptic and cognitive deficits." (PMID 36266523, 2023). "The USP25 gene has already been shown to be greatly expressed in the brains of DS patients than in controls and overexpression of USP25 in a murine model of DS-AD, particularly in hippocampal CA1 cells, results in microglial activation inducing both synaptic and cognitive deficits." (PMID 35585302, 2022).
colitis (4 papers, 2021 to 2025). Inflammation of the colon. "In DSS-induced colitis models, USP25-deficient mice exhibit increased leucocytes, CD8+ T cells, and CD11b+F4/80+ macrophages, and decreased infiltration of CD4+IL-17A+ T cells and CD11b+Gr-1+ neutrophil in the colonic lamina propria." (PMID 35145062, 2022). "When subjected to DSS-induced colitis, the intestines of USP25-deficient mice exhibit increased quantities of Paneth and goblet cells in the villi, and greater damage to the remaining epithelium and intestinal epithelium than those of USP25-sufficient mice." (PMID 35145062, 2022). "Therefore, increased secretory cell levels and elevated TLR signalling in secretory cells and IECs may contribute to the protection against DSS-induced colitis in USP25-deficient intestines." (PMID 35145062, 2022). "An adeno-associated virus 8 (AAV8) expression vector Usp25 (AAV–Usp25) was used to overexpress USP25 and subsequently induce colitis in DSS mice." (PMID 39773987, 2025). "To further verify the protective effect of USP25 in colitis, we examined the therapeutic effect of Usp25 in DSS-induced colitis in mice." (PMID 39773987, 2025). "This study further demonstrates that USP25 deficiency positively alters cytokine expression and protects mice against DSS-induced colitis." (PMID 35145062, 2022). "Results show that the expression of USP25 is decreased in patients with UC and mice with dextran sulfate sodium salt (DSS)-induced colitis and that USP25 deficiency exacerbates UC by destroying the intestinal mucosal barrier, however, overexpression of USP25 can alleviate colitis." (PMID 39773987, 2025). "Further, this study demonstrates the aggravation of DSS-induced colitis by intestinal epithelial cell-specific knockout Stat3 in mice, while Stat3 overexpression by adeno-associated virus attenuates colitis in DSS-induced Usp25−/− mice." (PMID 39773987, 2025). "Furthermore, when mouse colitis is associated with bacterial infection, USP25 can aggravate colitis by promoting STAT3 phosphorylation, consistent with previous studies, our study found that USP25 aggravates AP by regulating STAT3 (especially p-STAT3)." (PMID 35096833, 2021). "In this study, we showed that USP25 was downregulated in patients with UC and dextran sulfate sodium salt (DSS)-induced colitis." (PMID 39773987, 2025). "USP25 loss and DSS-induced colitis resistance in nonhematopoietic cells are prevalent in immune cell homoeostasis of the colon lamina propria." (PMID 35145062, 2022). "However, currently, no studies on the regulation of STAT3 expression by USP25 in colitis exist." (PMID 39773987, 2025).
colon cancer (4 papers, 2024 to 2025). "Downregulation of TRIM25 leads to an increase in USP25 levels, which in turn induces chemoresistance in colon cancer cells." (PMID 38803048, 2024). "We next treated the high USP25 level colon cancer cells SW620 with the peptides and found that the combination of PSH‐1 or PSH‐4 with 5‐Fu killed cancer cells more efficiently." (PMID 38803048, 2024). "Depletion of USP25 sensitizes colon cancer cells to IR, 5‐Fu, and cisplatin." (PMID 38803048, 2024). "Interestingly, USP25 protein levels were found higher in several colon cancer cell lines compared to normal cell lines, and a similar phenotype was observed in colon tumor samples." (PMID 38803048, 2024). "Moreover, inhibiting USP25 could temper KRAS signaling in pancreatic, lung, and colon cancer cells carrying various activating mutations in KRAS and for one of the mutants, KRASQ61H, no direct inhibitors are available." (PMID 40473213, 2025). "Importantly, we find that USP25 is overexpressed in a subset of colon cancers." (PMID 38803048, 2024). "Strong correlations between USP25 expression and that of RAS were detected across lung, pancreatic, and colon cancers." (PMID 40473213, 2025). "Conversely, knockdown TRIM25 rendered colon cancer cells resistant to 5‐Fu treatment in ctrl cells but not USP25‐depleted SW480 cells." (PMID 38803048, 2024). "Through analysis of the Ualcan dataset and quantitative PCR (qPCR) of colon cancer cell lines, we observed no change in USP25 mRNA levels between colon cancer and normal tissues, the cell lines showed similar results." (PMID 38803048, 2024). "To determine if pharmacological inhibition of USP25 is effective in reducing the expression levels of KRAS protein and in tempering KRAS signaling, we treated HT29 colon cancer cells (which do not harbor mutations in KRAS) with different concentrations of CT1113." (PMID 40473213, 2025). "In addition, USP25 expression in tumor tissues of lung and colon cancer samples is notably elevated compared to the adjacent noncancerous tissues." (PMID 40473213, 2025). "USP25 plays a role in promoting non-homologous end-joining (NHEJ), a DNA repair pathway that contributes to chemoresistance in colon cancer cells." (PMID 41321637, 2025). "We also observed a negative correlation between USP25 and TRIM25 protein expression in the colon tumor samples." (PMID 38803048, 2024).
pancreatic cancer (4 papers, 2022 to 2025). "It has been reported that USP25 depletion significantly changes the glycolytic metabolic pathway in pancreatic cancer." (PMID 40379626, 2025). "Moreover, the expression of USP25 is inversely correlated with patient survival in lung, colon, and pancreatic cancers." (PMID 40473213, 2025).
acute pancreatitis (3 papers, 2021 to 2025). An acute inflammatory process that leads to necrosis of the pancreatic parenchyma. "Furthermore, USP25 is significantly upregulated in acute pancreatitis models and is implicated in the activation of GSDMD-mediated pyroptotic cell death in acinar cells during acute pancreatitis." (PMID 40307577, 2025). "USP25 facilitated pro-inflammatory factor production and tight junction impairment via STAT3 pathway, causing exacerbated acute pancreatitis (AP) and AP-related organ injury." (PMID 37814350, 2023). "Noticeably, USP25 upregulation was reported to boost NLRP3 inflammasome-mediated pyroptosis of acinar cells in acute pancreatitis." (PMID 37814350, 2023). "We are grateful to healthy controls and acute pancreatitis patients who provided serum samples and appreciate Chen Dong who kindly provided USP25 knockout mice for us." (PMID 35096833, 2021). "However, the role of USP25 in acute pancreatitis (AP) is still unclear." (PMID 35096833, 2021). "However, the role of USP25 and its mechanism in acute pancreatitis remains unclear." (PMID 35096833, 2021).